NFKBIL1 (NFKB inhibitor like 1)
Description:
Involved in the regulation of innate immune response. Acts as negative regulator of Toll-like receptor and interferon-regulatory factor (IRF) signaling pathways. Contributes to the negative regulation of transcriptional activation of NF-kappa-B target genes in response to endogenous proinflammatory stimuli.
Synonyms: IKBL; NFKBIL
Tractability: PROTAC: ubiquitination databases record sites on it.
Gene: Protein-coding gene on chromosome 6 (31,546,870 to 31,558,829, forward strand). Ensembl gene ENSG00000204498.
Subcellular location: Nucleus
Subcellular location (Human Protein Atlas): Nucleoplasm
Gene Ontology:
Molecular function: protein binding; transcription regulator inhibitor activity
Biological process: cellular response to lipopolysaccharide; negative regulation of lipopolysaccharide-mediated signaling pathway; negative regulation of toll-like receptor signaling pathway; negative regulation of tumor necrosis factor production; negative regulation of canonical NF-kappaB signal transduction; negative regulation of signal transduction; regulation of gene expression
Cellular component: nucleoplasm; nucleus
Genetic constraint (gnomAD): Loss-of-function variants: 29 observed, 40.33 expected, observed/expected ratio (o/e) 0.72, 90% interval 0.53 to 0.98. The upper end of that interval is the gene's LOEUF score, 0.98, which puts it in group 4 of 6, group 1 being the genes least tolerant of losing a copy. Missense variants: 429 observed, 455.08 expected, observed/expected ratio (o/e) 0.94, 90% interval 0.87 to 1.02. Synonymous variants: 176 observed, 173.37 expected, observed/expected ratio (o/e) 1.02, 90% interval 0.9 to 1.15.
Homologues: Orthologues: macaque NFKBIL1 (99% identical), chimpanzee NFKBIL1 (95% identical), pig NFKBIL1 (95% identical), dog NFKBIL1 (93% identical), rat Nfkbil1 (92% identical), mouse Nfkbil1 (92% identical), guinea pig NFKBIL1 (84% identical), rabbit NFKBIL1 (83% identical), zebrafish nfkbil1 (32% identical), tropical clawed frog nfkbil1 (32% identical).
Diseases named in the same sentence as NFKBIL1 in open-access papers:
NFKBIL1 is named in the same sentence as 24 diseases in open-access papers, as found by Europe PMC text mining. Sharing a sentence is not in itself a finding about the gene and the disease. The quoted sentences say what the papers report.
rheumatoid arthritis (4 papers, 2011 to 2021). A chronic, systemic autoimmune disorder characterized by inflammation in the synovial membranes and articular surfaces. "Genetic variations in NFKBIL1 are associated with susceptibility to inflammatory conditions such as periodontitis, chronic thromboembolic pulmonary hypertension, rheumatoid arthritis, and malaria." (PMID 25038626, 2014). "NFKBIL1 has also been associated with autoimmune disorders such as rheumatoid arthritis, SLE and Sjogren's syndrome." (PMID 22125590, 2011).
autism (1 paper, 2020). Persistent deficits in social interaction and communication and interaction as well as a markedly restricted repertoire of activity and interest as well as repetitive patterns of behavior. "There is recent speculation of genetic association between an SNP in NFKBIL1 and autism-like traits." (PMID 33374967, 2020).
colorectal carcinoma (1 paper, 2022). A malignant epithelial neoplasm that arises from the colon or rectum and invades through the muscularis mucosa into the submucosa. "The NFKBIL-1 protein was shown recently to be a potential biomarker of diabetes-related colorectal carcinoma." (PMID 35328735, 2022).
follicular lymphoma (1 paper, 2009). Follicular lymphoma is a form of non-Hodgkin lymphoma characterized by a proliferation of B cells whose nodular structure of follicular architecture is preserved. "Evaluation of the region using a sliding window of three loci revealed the NFKBIL1 region to also be significantly associated with NHL, including follicular lymphoma." (PMID 19390683, 2009).
hyperuricemia (1 paper, 2018). An abnormally high level of uric acid. "Of these SNVs, nine are located at seven gene loci (DDX39B, NFKBIL1, CDC42BPG, CDC63, BRAP, ACAD10, and PCNX3) that might be novel susceptibility loci for hyperuricemia." (PMID 29124443, 2018).
myocardial infarction (1 paper, 2022). Gross necrosis of the myocardium, as a result of interruption of the blood supply to the area, as in coronary thrombosis. "Recent evidence has shown an association between three polymorphisms of these genes [BAT1 rs2239527 C/G, NFKBIL1 rs2071592 T/A, and LTA rs1800683 A/G] with the presence of acute coronary syndrome (ACS), myocardial infarction, and hypertension." (PMID 35740890, 2022). "Recent studies have shown that the polymorphisms (BAT1 rs2239527 C/G, NFKBIL1 rs2071592 T/A, LTA rs1800683 G/A, CASP1 rs501192 A/G, and CASP1 rs580253 A/G) are associated with the presence of ACS, myocardial infarction, and CAD." (PMID 35740890, 2022).
psoriasis (1 paper, 2011). An autoimmune condition characterized by red, well-delineated plaques with silvery scales that are usually on the extensor surfaces and scalp. "In addition to classical HLA genes such as HLA-C, HLA-B and HLA-DQA2, we also find association of non-HLA genes in the MHC region such as POU5F1, NFKBIL1, NOTCH4, MICA, IER3 and OR12D2 with psoriasis." (PMID 22125590, 2011).
cancer (2 papers, 2019 to 2021). A tumor composed of atypical neoplastic, often pleomorphic cells that invade other tissues. "In addition, a series of genetic variants in MICA, MICB, NFKBIL1, SLC6A3, CLPTM1L, and TERT have been found to be associated with the susceptibility and prognosis of different cancer types." (PMID 35003220, 2021). "The 3’UTR of several hallmark genes such as Cyclin-dependent kinase 2 (CDK2), Cyclin-dependent kinase 16 (CDK16), MAPK1 and NFKBIL1 are significantly longer in HPV positive cancer compared with HPV negative cancer." (PMID 31039132, 2019).
NFKBIL1 also shares sentences with these, for which no sentence is quoted: chronic periodontitis (2 papers); systemic lupus erythematosus (2); autoimmune disorders (1); autoimmune thyroid disease (1); biliary tract cancer (1); chronic thromboembolic pulmonary hypertension (1); Cirrhosis (1); cognitive deficits (1); dental caries (1); diabetes (1); Graves disease (1); infection (1); malaria (1); marginal zone lymphoma (1); Sjogren syndrome (1); tuberculosis (1).